MPO (myeloperoxidase)
Diseases named in the same sentence as MPO in open-access papers (continued):
Sharing a sentence is not in itself a finding about the gene and the disease.
diabetes (114 papers, 2009 to 2026). "To address this gap, we employed an optimized immunocapture assay to evaluate MPO activity, specific activity, and protein concentration in females with type 2 diabetes mellitus (T2DM), a condition tightly linked to chronic low-grade inflammation and obesity." (PMID 41596188, 2026). "In conclusion, this study is the first to reveal a U-shaped relationship between plasma MPO and anxiety risk and to identify diabetes as a factor that exacerbates MPO-related anxiety risk." (PMID 40401059, 2025). "More pointedly, early clinical trials of aminoguanidine to prevent microvascular disease in patients with diabetes were complicated by several cases of overt MPO antibody associated ANCA vasculitis, which presented as crescentic glomerulonephritis." (PMID 40020049, 2025). "This unusual appearance is typical of MPO deficiency, which is frequently asymptomatic in individuals unless there are specific cases such as diabetes." (PMID 39087142, 2024). "AOPP content is correlated with serum MPO in pathological conditions such as diabetes or uremia, and it is worth studying if these hypochlorite-modified adducts are linked to changes in MPO in PD." (PMID 35739985, 2022). "In the present study, we found for the first time that serum MPO activities were significantly associated with angiographically documented coronary artery plaque progression in patients with diabetes." (PMID 36404308, 2022). "MPO has been linked to the pathogenesis of numerous diseases, including inflammatory, neurodegenerative diseases, obesity, diabetes, cancer, and heart disease, in which chronic or acute inflammatory processes are often present." (PMID 36552200, 2022). "Diabetes is associated with higher concentration of MPO and at the same time with lower concentration of PON-1." (PMID 36463116, 2022). "In this study, we evaluated the association between type 2 diabetes mellitus and the concentrations of MPO and PON-1 in patients with IHD." (PMID 36463116, 2022). "Both IL-6 expression and MPO activity are predictors of obesity-associated morbidities, pre-diabetes, and cardiovascular diseases." (PMID 32077465, 2020). "Several types of tissue injuries and the pathogenesis of several other major chronic diseases such as rheumatoid arthritis, cardiovascular diseases, liver diseases, diabetes, and cancer have been reported to be linked with MPO-derived oxidants." (PMID 29669993, 2018). "In this study, diabetes caused elevations of cardiac MPO activity, a marker of neutrophil infiltration and inflammation indicating the presence of enhanced neutrophil recruitment in the inflamed tissues." (PMID 29959408, 2018). "Several inflammatory diseases such as endometriosis, polycystic ovarian syndrome, diabetes, are not only associated with increased ROS production but also increased MPO levels." (PMID 26982351, 2016). "Inherited MPO deficiency is frequent in humans, but MPO-deficient individuals are mostly asymptomatic, except for a small subset that suffers from diabetes." (PMID 25764063, 2015). "Recurrent Candida infection has been observed predominantly in MPO-deficient patients that also have diabetes mellitus." (PMID 24385801, 2013). "Monitoring MPO may aid in risk stratification and personalized interventions, particularly in populations with diabetes." (PMID 40401059, 2025). "Given that MPO elevation predicts diabetes and cardiovascular risk, MPO suppression could improve outcomes in aging patients." (PMID 41394145, 2025). "Our study also identified that diabetes may exacerbate MPO-induced anxiety risk, which could be attributed to the significantly elevated plasma MPO observed in type 2 diabetes patients." (PMID 40401059, 2025). "In addition, increased levels of MPO encapsulated in exosomes or extracellular vesicles were associated with various diseases, such as type 2 diabetes mellitus and deep venous thrombosis." (PMID 38888462, 2024).
diabetes (continued). "MPO deficiency is a rare condition often characterized by a lifelong history of recurrent infections, although most patients remain asymptomatic except for those with diabetes." (PMID 39087142, 2024). "However, myeloperoxidase deficiency is associated with a greater risk of infection by C. albicans in patients with other underlying diseases such as diabetes." (PMID 38032204, 2023). "The fact that MPO deficiency can be easily overcome is in line with clinical data, as patients with partial or total MPO deficiency are not usually seen to be hypersusceptible to infections except those with underlying comorbidities, such as diabetes mellitus." (PMID 32341348, 2020). "Similarly, patients with a genetic polymorphism resulting in decreased expression of MPO have a higher risk of developing autoimmune lupus nephritis, and MS and diabetes patients have been reported to have lower MPO activity in their blood leukocytes." (PMID 26904693, 2016). "Therefore, drugs that have the potential to influence both vascular function and MPO have become highly interesting, especially if already used in the treatment of other CV risk factors in persons with diabetes." (PMID 24594096, 2014). "The first one assumes that a higher concentration of AOPPs in plasma is associated with increasing MPO enzyme levels in the plasma and consequently associated with oxidative/chlorine stress, which leads to the accumulation of modified proteins in the condition of diabetes." (PMID 33333730, 2020). "Yet, the majority of myeloperoxidase-deficient patients are asymptomatic, and invasive candidiasis develops only in patients with autosomal-recessive complete myeloperoxidase deficiency who also have concomitant disorders that adversely affect phagocyte function such as diabetes." (PMID 23300452, 2013). "Patients with comorbidities, such as high blood pressure or diabetes, showed minimal MPO responses, potentially due to the influence of these conditions on inflammatory thresholds." (PMID 39852209, 2025). "Type 2 diabetes mellitus is accompanied by halogenated stress as neutrophilic MPO generates highly reactive hypochlorous acid (HOCl), which can modify serum albumin (Cl-HSA)." (PMID 39875729, 2025). "Diabetes-induced MPO elevation likely triggers chronic inflammation, intensifying neuroinflammatory responses." (PMID 40401059, 2025). "Patients with comorbidities, such as diabetes and hypertension, often displayed lower MPO responses, suggesting altered inflammatory thresholds." (PMID 39852209, 2025). "For example, patients suffering from conditions such as high blood pressure, cholesterol, and diabetes (e.g., N4, N5, N9) demonstrated distinct MPO and IL-6 responses." (PMID 39852209, 2025). "Consistent with the cell culture transwell migration assay, pharmacological inhibition of GSK3β by VP3.15 also reduced a diabetes-induced increase in F4/80 +ve and myeloperoxidase (MPO) +ve immune cell infiltration into glomeruli of diabetic mice." (PMID 39880090, 2025). "Additionally, we identified that diabetes may exacerbate MPO-related anxiety risk." (PMID 40401059, 2025). "LDN counts in patients with diabetes were significantly higher (160%), along with circulating NETs biomarkers (citrullinated H3 histone (H3Cit), myeloperoxidase (MPO), and MPO-DNA (137%, 175%, and 69%, respectively) versus HV." (PMID 38338951, 2024). "MPO has been incriminated in the pathogenesis of multiple chronic diseases such as diabetes, arthritis, liver diseases, cardiovascular diseases, cancer, and various types of tissue insults." (PMID 38785813, 2024). "Sustained NLRP3 inflammasome activation with infiltration of neutrophils was reported in diabetes, in line with the observation that BI-1–/– mice presented more MPO-positive cells in pancreatic sections that were corrected with IRE1α RNase inhibition." (PMID 38744890, 2024).
diabetes (continued). "In general, to test the NETosis in diabetes is combined with many indictors such as MPO, NE, PR3, PAD4, LL37(an antimicrobial cathelicidin) and cell-free DNA-histone by ELISA." (PMID 37600700, 2023). "Comorbidities, namely obesity, diabetes, and ageing generate inflammation, during which MPO is released and uses H2O2 as a substrate toproduce hypochlorous acid, a potent pro-oxidant and proinflammatory molecule." (PMID 39077419, 2023). "Patients with MPO levels above the mediansuffered more often from diabetes (48 vs 18%, p = 0.017) and were moreoften males (48 vs 21%, p = 0.037) than patients with MPO levels belowthe median." (PMID 39077419, 2023). "Patients with levels of MPO above themedian are more often males and suffer more often from diabetes." (PMID 39077419, 2023). "MPO is incriminated in several major pathologies, such as liver disease, rheumatoid arthritis, cancer, and diabetes." (PMID 37959383, 2023). "By co-labeling of CITH3 and MPO, typical NETs is observed in the vitreous and retina in patients with diabetes, showing decompressed DNA structures and co-localized proteins, suggesting that NETs formation takes a part in the pathogenesis of DR." (PMID 37600700, 2023). "The only parameter with an independent impact on MPO concentrations was the presence of diabetes alone." (PMID 36463116, 2022). "Multivariable logistic regression analysis revealed that serum MPO levels and activities are independent determinants of plaque progression in patients with diabetes." (PMID 36404308, 2022). "MPO strongly oxidizes apolipoprotein A-I of HDL in patients with diabetes, which results in rampant impairment of cholesterol transport." (PMID 36404308, 2022). "After adjustment for age, sex, hypertension, diabetes mellitus, eGFR, and NT-proBNP, high plasma levels of MPO and TMAO remained an independent predictor of MACEs at 6 months (HR: 11.88, 95% CI: 1.54–91.46, p = 0.017)." (PMID 34650427, 2021). "The proportion of patients who were smokers, had diabetes, and hypertension, and were dialysis-dependent was 38.1%, 28.9%, 82.1%, and 40.2% in the MPO-AAV group, and 54.0%, 36.5%, 78.7%, and 47.0% in the control group, respectively." (PMID 33481903, 2021). "For this purpose, myeloperoxidase (MPO) and elastase (EL) were jointly analyzed in the blood plasma from 160 type 2 diabetes mellitus patients with high levels of HbA1c." (PMID 32908806, 2020). "Diabetes mellitus development was accompanied with violation of neutrophils and lymphocytes proliferation, increased activity of myeloperoxidase and enhanced apoptosis process." (PMID 29310643, 2018). "Diabetes mellitus development was accompanied by violation of neutrophils and lymphocytes proliferation, increased activity of granulocytes MPO and enhanced lymphocytes apoptosis." (PMID 29310643, 2018). "The liraglutide pretreatment diabetes ischemia group of SOD and MPO enzyme increases significantly compared to the diabetes complicated with cerebral ischemia group." (PMID 29623090, 2018). "In humans, a strong positive correlation has been found between obesity and diabetes with leukocytosis, as the plasma MPO level was found to be raised in prepubertal obese children." (PMID 29669993, 2018). "The relationship between type 2 diabetes mellitus and MPO has been investigated by previous studies, which arrived at contradicting conclusions." (PMID 26719776, 2015). "Our findings also link inflammatory conditions related to poor reproductive outcomes such as diabetes, endometriosis and others with oocyte aging or deterioration of oocyte quality from elevated MPO levels." (PMID 26197395, 2015). "In clinical studies, statins reduced circulating levels of MPO in patients with congestive heart failure, acute coronary syndromes and patients with diabetes on dialysis." (PMID 24594096, 2014).
diabetes (continued). "Overall, the inflammatory parameters (neutrophil accumulation - myeloperoxidase activity, tumor necrosis factor alpha, and monocyte chemotactic protein-1 levels and mast cell counting) increased in subcutaneous implants after diabetes induction." (PMID 25372281, 2014). "Global markers of inflammation, CRP and MPO levels in plasma, were significantly higher in obese participants with diabetes before treatment compared to controls, supporting the pro-inflammatory state expected in this population." (PMID 23025537, 2012). "Remarkably, metformin reduced neutrophil accumulation in the surrounding tissue, as demonstrated in a previous study, suggesting its capacity to reduce oxidative stress, myeloperoxidase activity, and tissue damage in animal models of diabetes and prostate cancer." (PMID 41346233, 2026). "Diabetes induction in rats increased their susceptibility to diabetes vascular complications, leading to dyslipidemia and elevating cardiovascular indices (LDL/HDL, MPO/HDL, and MPO/PON-1) (respectively)." (PMID 39877627, 2025). "Interestingly, our subgroup analysis showed that participants in the highest MPO quintile (Q5) were, on average, younger and had lower prevalence of chronic conditions such as diabetes and hypertension." (PMID 40401059, 2025). "In metabolic diseases such as diabetes, neutrophils often exhibit functional impairments (e.g., reduced chemotaxis, phagocytosis, and activation), which may lead to decreased MPO activity." (PMID 41465092, 2025). "Further studies are required to definitively decipher the true significance of the aggravated stimulation of MPO, iNOS and eNOS synthesis following vitamin D3 treatment that could help to better understand its protective effects in diabetes." (PMID 40776976, 2025). "Indeed, all men suffering from diabetes had MPO levels abovethe median, while the proportion was limited to 40% in the other subgroups." (PMID 39077419, 2023). "This study aimed to investigate whether the serum levels and activities of MPO are related to coronary plaque progression in patients with type 2 diabetes mellitus (T2DM)." (PMID 36404308, 2022). "Our study showed a significantly higher concentration of MPO in patients with IHD and diabetes, which may be one of the mechanisms associated with HDL particles “dysfunction” in this patient group." (PMID 36463116, 2022). "MPO can enhance high glucose-induced vascular injury in diabetes." (PMID 36404308, 2022). "Patients with diabetes showed significantly higher MPO concentration levels in serum, P = 0.02." (PMID 36463116, 2022). "Thus, plasma glucose and MPO levels constitute indicators of HDL dysfunction and contribute to risk stratification in patients with diabetes." (PMID 36404308, 2022). "We categorized these patients with diabetes into MPO level or activity tertile subgroups." (PMID 36404308, 2022). "Finally, the inhibition of MPO activity was described in the case of type 2 diabetes mellitus as well as in the case of interaction HSA-MG with MPO in vitro." (PMID 36421449, 2022). "In other studies performed in non-inflammatory diseases, MPO was associated with IMT in metabolic syndrome but not in type 2 diabetes mellitus." (PMID 34680168, 2021). "Therefore, it can be argued that MPO and EL really take an active part in numerous pathological processes in diabetes." (PMID 32908806, 2020). "Diabetes mellitus has been found to increase MPO levels in some humans, whereas other studies suggest that it may falsely lower the level of MPO." (PMID 32442236, 2020). "Another disease that can influence MPO levels in humans is diabetes mellitus." (PMID 32442236, 2020). "Nonetheless, the role of MPO in diabetes is still ambiguous as the findings are contrasting." (PMID 32277104, 2020). "Thus, the conjoint MPO/EL measurements confirm the leading role of PMNs in the development of various complications of diabetes." (PMID 32908806, 2020).
diabetes (continued). "Given the variable influence diabetes can have on MPO activity in people, we elected to include diabetics in this study to evaluate for any identifiable influence that diabetic status could have on uMPO concentrations in canines." (PMID 32442236, 2020). "Furthermore, different studies have shown that increased levels of MPO, IL-6 and hs-CRP are significantly associated with an increased risk of diabetes." (PMID 32650465, 2020). "MPO is an important factor in the inflammatory response, the determination of the increase of MPO can be confirmed to be one of the mechanisms of cerebral ischemia aggravated diabetes." (PMID 29623090, 2018). "NO increases in some chronic diseases such as diabetes.Moreover, NO has anti-inflammatory and anti-atherogenic activities.Myeloperoxidase (MPO) is an enzyme that is released by activated neutrophils, monocytes, and tissue-associated macrophages after inflammatory stimuli." (PMID 28975102, 2017). "Indeed, besides the potential role of NETosis in exacerbating small-vessel vasculitis or microvascular occlusions due to the formation of anti-NE or anti-MPO autoantibodies found in NETs, both diabetes and DR progression seem to be characterized by NETs’ enhanced formation and release." (PMID 38256379, 2024). "Similarly, MPO HKOs are usually asymptomatic, not displaying an increased susceptibility to infections, unless specific comorbidities occur (i.e., diabetes mellitus)." (PMID 33727708, 2021). "Despite the requirement of MPO to generate NETs and its highly effective antimicrobial properties, a genetic deficiency in MPO does not appear to have a major impact on individuals with this defect, they generally live healthy lives unless they have co-morbidities such as diabetes." (PMID 33790907, 2021). "The present study, indicates that myeloperoxidase levels are reduced with empagliflozin, suggesting that this may be the way in which empagliflozin prevents the oxidative damage to the endothelium that precedes many of the complications of diabetes." (PMID 31683785, 2019). "The results show that SOD and MPO are significantly higher in the diabetes complicated with cerebral ischemia group than in the sham operation group, and it is confirmed that DM is one of the most important factors in cerebral ischemia injury." (PMID 29623090, 2018). "Moreover, in type 1 diabetes mellitus, activated neutrophils contribute to the pathogenetic process, especially via the granular proteolytic enzymes NE and MPO, which may originate from enhanced NET formation." (PMID 27679792, 2016). "Furthermore, a patient level meta-analysis between HEMO and MPO should be undertaken to corroborate the impression that the flux effect appears to be larger in patients with hypo-albuminemia and diabetes while examining the cardiovascular and infectious components of mortality." (PMID 26057383, 2015). "Cit-H3 was colocalised with myeloperoxidase (MPO) and NIMP-R14 in db/db mice with 4 and 7 months of diabetes duration." (PMID 39875729, 2025). "Sex, age, diabetes, hypertension, GPA vs. MPA AAV, PR3-ANCA or MPO-ANCA antibody profile, or glucocorticoid treatment were all non-influential." (PMID 36013990, 2022). "Further, ΔpbsP mutant–infected tissues have significantly less abundance of neutrophil markers MPO, elastase, and calprotectin, which are all up-regulated during GBS diabetic wound infection." (PMID 36367946, 2022). "Patients with higher plasma levels of MPO and TMAO were more likely to be older, have diabetes mellitus, have reduced renal function, and have higher NT-proBNP level." (PMID 34650427, 2021). "However, after adjustment for age, sex, hypertension, diabetes mellitus, eGFR, and NT-proBNP, the association between log MPO and increased risk of MACEs and death at 6 months became nonsignificant (HR: 2.34, 95% CI: 0.98–5.61, p = 0.056; HR: 3.08, 95% CI: 0.94–10.06, p = 0.062, respectively)." (PMID 34650427, 2021).